TMEM59 (transmembrane protein 59)
Description:
Acts as a regulator of autophagy in response to S.aureus infection by promoting activation of LC3 (MAP1LC3A, MAP1LC3B or MAP1LC3C). Acts by interacting with ATG16L1, leading to promote a functional complex between LC3 and ATG16L1 and promoting LC3 lipidation and subsequent activation of autophagy. Modulates the O-glycosylation and complex N-glycosylation steps occurring during the Golgi maturation of several proteins such as APP, BACE1, SEAP or PRNP. Inhibits APP transport to the cell surface and further shedding.
Synonyms: C1orf8; HSPC001; DCF1; PRO195; UNQ169
Tractability: Antibody: UniProt places it where antibodies can reach, with high confidence; UniProt predicts a signal peptide or a membrane-spanning region; its Gene Ontology location is reachable by antibodies, with medium confidence. PROTAC: ubiquitination databases record sites on it.
Gene: Protein-coding gene on chromosome 1 (54,026,681 to 54,053,504, reverse strand). Ensembl gene ENSG00000116209.
Subcellular location: Late endosome membrane; Lysosome membrane; Cell membrane; Golgi apparatus membrane
Pathways (Reactome):
Signal Transduction: RHOH GTPase cycle; RND1 GTPase cycle
Gene Ontology:
Molecular function: protein binding; endopeptidase activity
Biological process: glycoprotein biosynthetic process; negative regulation of protein localization to plasma membrane; positive regulation of autophagy
Cellular component: extracellular exosome; Golgi cis cisterna; Golgi medial cisterna; Golgi membrane; Golgi trans cisterna; late endosome; lysosome; late endosome membrane; lysosomal membrane; plasma membrane
Genetic constraint (gnomAD): Loss-of-function variants: 29 observed, 30.19 expected, observed/expected ratio (o/e) 0.96, 90% interval 0.71 to 1.31. The upper end of that interval is the gene's LOEUF score, 1.31, which puts it in group 5 of 6, group 1 being the genes least tolerant of losing a copy. Missense variants: 345 observed, 361.3 expected, observed/expected ratio (o/e) 0.95, 90% interval 0.87 to 1.04. Synonymous variants: 146 observed, 143.78 expected, observed/expected ratio (o/e) 1.02, 90% interval 0.89 to 1.16.
Homologues: Orthologues: macaque TMEM59 (99% identical), chimpanzee TMEM59 (98% identical), dog TMEM59 (96% identical), rabbit TMEM59 (95% identical), guinea pig TMEM59 (95% identical), mouse Tmem59 (94% identical), rat Tmem59 (94% identical), pig TMEM59 (85% identical), tropical clawed frog tmem59 (59% identical), zebrafish tmem59 (59% identical). Paralogues in human: TMEM59L (33% identical).
Diseases named in the same sentence as TMEM59 in open-access papers:
TMEM59 is named in the same sentence as 22 diseases in open-access papers, as found by Europe PMC text mining. Sharing a sentence is not in itself a finding about the gene and the disease. The quoted sentences say what the papers report.
Alzheimer disease (5 papers, 2018 to 2025). A progressive, neurodegenerative disease characterized by loss of function and death of nerve cells in several areas of the brain leading to loss of cognitive function such as memory and language. "Transmembrane protein 59 (TMEM59) is correlated with Alzheimer's disease (AD), the most common type of tauopathy." (PMID 40551290, 2025).
Cognitive impairment (3 papers, 2020 to 2025). Abnormal cognition is characterized by deficits in thinking, reasoning, or remembering. "The role of TMEM59 haploinsufficiency in reducing pathology and cognitive impairment has been well documented in the 5xFAD mouse model of AD." (PMID 38444019, 2024). "Moreover, we show that TMEM59 haploinsufficiency attenuates cognitive deficits and disease‐related pathologies in PS19 mice." (PMID 40551290, 2025).
glioma (3 papers, 2018 to 2022). A benign or malignant brain and spinal cord tumor that arises from glial cells (astrocytes, oligodendrocytes, ependymal cells). "Out of the well-predicted genes, CDK4, MMP7, MYCBP, and TMEM59 in gliomas and LCP1 in RCC have been implicated in multiple cancer types." (PMID 32194984, 2020).
Anxiety (2 papers, 2020 to 2023). Intense feelings of nervousness, tension, or panic often arise in response to interpersonal stresses. "The time spent in the center and total moving distance in open field tests of 59+/– and 5xFAD; 59+/– mice were comparable to respective controls, suggesting that TMEM59 haploinsufficiency did not affect mouse locomotor activity and anxiety at this age." (PMID 33195275, 2020).
Parkinson disease (2 papers, 2011 to 2025). A progressive degenerative disorder of the central nervous system characterized by loss of dopamine producing neurons in the substantia nigra and the presence of Lewy bodies in the substantia nigra and locus coeruleus. "TREM2 can interact with Transmembrane Protein 59 (TMEM59), a membrane-bound protein, to enhance autophagy, which may protect dopaminergic neurons against inflammation-associated damage in Parkinson’s disease." (PMID 40806186, 2025).
autism (1 paper, 2023). Persistent deficits in social interaction and communication and interaction as well as a markedly restricted repertoire of activity and interest as well as repetitive patterns of behavior. "In a mouse model of microglial Tmem59 deletion, deletion of microglial Tmem59 impaired synaptic phagocytosis, leading to autism-like behavior." (PMID 37021129, 2023).
glioblastoma (1 paper, 2022). The most malignant astrocytic tumor (WHO grade IV). "Dcf1, also known as dendritic factor 1 or TMEM59, is a one‐pass transmembrane protein that has been demonstrated to play vital roles in glioblastoma cell lines in previous studies." (PMID 34799992, 2022).
memory impairment (1 paper, 2020). "Herein, we found that overexpression of TMEM59 in the hippocampal region led to memory impairment in wild type mice, suggesting its neurotoxic role." (PMID 33195275, 2020). "One research group reported that complete knockout and nervous system-specific knockout of Tmem59 resulted in memory impairments in mice." (PMID 33195275, 2020).
osteosarcoma (1 paper, 2022). A usually aggressive malignant bone-forming mesenchymal neoplasm, predominantly affecting adolescents and young adults. "Prognosis-related TMEM protein family genes were identified by the univariate Cox regression analysis and were utilized to construct a signature based on six TMEM protein family genes (TMEM120B, TMEM147, TMEM9B, TMEM8A, TMEM59, and TMEM39B) in osteosarcoma." (PMID 35991561, 2022). "In both cohorts, the expression levels of TMEM8A, TMEM39B, and TMEM59 were not related to the overall survival of osteosarcoma patients in the Kaplan–Meier survival analyses." (PMID 35991561, 2022).
Sepsis (1 paper, 2026). Sepsis is defined as life-threatening organ dysfunction caused by a dysregulated host response to infection. "qPCR results showed that the expression of S100A9, PCBP1, PIK3CB, FOXO1, and TMEM59 was consistent with the public dataset, among which S100A9, PIK3CB, and TMEM59 were significantly overexpressed in sepsis, whereas PCBP1 and FOXO1 were significantly underexpressed in sepsis." (PMID 41542228, 2026). "FOXO1, KLHL3, and PCBP1 were weakly expressed in the sepsis group whereas MTF1, TMEM59, PIK3CB, and S100A9 were highly expressed in the sepsis group." (PMID 41542228, 2026).
staphylococcus aureus infection (1 paper, 2023). An infectious process in which the bacteria Staphylococcus aureus is present. "Endogenous TMEM59 interacts with ATG16L1 and mediates autophagy in response to Staphylococcus aureus infection." (PMID 37511481, 2023).
tauopathy (1 paper, 2025). Neurodegenerative disorders involving deposition of abnormal tau protein isoforms (tau proteins) in neurons and glial cells in the brain. "In addition to HSC70, our RNA‐seq and mass spectrometry results identified many other genes/proteins involved in misfolded protein responses, implying that these pathways may also participate in TMEM59 deficiency‐mediated protection in tauopathy." (PMID 40551290, 2025). "Our study identifies an important role of TMEM59 in regulating CMA and reveals the potential of targeting TMEM59 for tauopathy intervention." (PMID 40551290, 2025). "In conclusion, our study not only demonstrates that TMEM59 plays an important role in tauopathy but also identifies a crucial function of TMEM59 in binding HSC70 and LAMP2A to regulate the CMA activity." (PMID 40551290, 2025). "We analyzed TMEM59 levels in the brains of AD patients and the tauP301S transgenic (PS19) mice, evaluated behaviors and tauopathy‐related pathologies in PS19 mice with TMEM59 haploinsufficiency, and studied the regulation of TMEM59 on chaperone‐mediated autophagy (CMA) using biochemical analysis." (PMID 40551290, 2025). "Because TMEM59 expression is increased in the brain of AD patients and tauopathy model mice, we next studied whether TMEM59 reduction can alter memory and synaptic plasticity in PS19 mice." (PMID 40551290, 2025). "Herein, we find that TMEM59 protein levels increase in the brains of AD patients and the tauP301S transgenic (PS19) tauopathy mouse model at pathological stages." (PMID 40551290, 2025).
cancer (6 papers, 2020 to 2023). A tumor composed of atypical neoplastic, often pleomorphic cells that invade other tissues. "It follows that the C60 nanofilm inhibited autophagy by reducing the level of the TMEM59 protein and thus limited the supply of nutrients needed for excessive cell proliferation in advanced cancer stages." (PMID 38067256, 2023). "The in-situ cancer-2 population shows a strong and specific expression of TMEM59 and SOX4, which both can promote apoptosis." (PMID 35835774, 2022). "Several of these HSEPs have been reported in other contexts to play key roles in tumour progression by cancer cell proliferation (NRSN2, WISP2, SPRX1, LCK), metastasis (GOLM1, STC1, MGAT5B), and stemness (STC1, TMEM59), as well as promoting angiogenesis (ANGPTL4) and host immunosuppression (CD70)." (PMID 33050615, 2020).
tumor (6 papers, 2020 to 2026). "Under hypoxic conditions, A549 lung cancer cells synthesize EVs containing TMEM59, which is associated with enhancing tumor cell stemness." (PMID 41596760, 2026). "TMEM59, also known as DCF1, C1orf8, PRO195, UNQ169, and HSPC001, is a protein that has been implicated in modulation of the tumor microenvironment through EVs." (PMID 41596760, 2026). "Until now, the role of TMEM59 in tumors is relatively understudied and further experiments need to be performed to investigate the function of TMEM59 in the malignant behaviors of tumor cells." (PMID 35991561, 2022). "In the tumor microenvironment, the up-regulation of three TMEM genes (TMEM204, TMEM88, and TMEM59) in endothelial cells caught our attention." (PMID 37265785, 2023). "It was suggested that BF-TK/GCV significantly upregulated TMEM59 and ATG16, indicating the potential of inhibiting tumor metastasis." (PMID 37511481, 2023). "The presence of TMEM215 in endothelial cells, TMEM59 in hypoxic tumor-derived extracellular vesicles, and late B cells indicates that TMEM-directed therapies may reshape the tumor microenvironment." (PMID 41596760, 2026). "Additionally, numerous studies have shown that TMEM123 and TMEM66 in T cells, and TMEM208, TMEM59, and TMEM258 in B cells, are closely related to inflammatory response and participate in tumor immune response, which is consistent with our findings." (PMID 37265785, 2023). "The results revealed that hypoxia stimulated cells to synthesize EVs proteins involved in enhancing tumour cell proliferation (NRSN2, WISP2, SPRX1, LCK), metastasis (GOLM1, STC1, MGAT5B), stemness (STC1, TMEM59), angiogenesis (ANGPTL4), and suppressing host immunity (CD70)." (PMID 33050615, 2020).
bacterial infection (4 papers, 2016 to 2024). "For instance, autophagy can be induced by Autophagy related 16 like 1 (ATG16L1)-Transmembrane protein 59 (TMEM59) interactions in response to bacterial infection." (PMID 35694307, 2022). "Such alteration impairs the unconventional autophagic activity of TMEM59, a transmembrane protein that contains the WD40 domain-binding motif, and disrupts its normal intracellular trafficking and its ability to engage ATG16L1 in response to bacterial infection." (PMID 27273576, 2016).
infection (2 papers, 2016 to 2020). The state of being infected such as from the introduction of a foreign agent such as serum, vaccine, antigenic substance or organism. "We found that, at early infection time points (2 h post-infection), TMEM59 associated defectively with ATG16L1-A300 compared with the T300 form." (PMID 27273576, 2016). "The expression of both SNX14 and TMEM59 was enhanced by Myr upon infection, suggesting that the compound drives a pathogen-clearance-related autophagy." (PMID 32781626, 2020).
TMEM59 also shares sentences with these, for which no sentence is quoted: dementia (1 paper); Depression (1); Hypertension (1); Mediterranean fever (1); neurodegenerative disease (1); stomach cancer (1).